H6PD (hexose-6-phosphate dehydrogenase/glucose 1-dehydrogenase)
Diseases named in the same sentence as H6PD in open-access papers (continued):
Sharing a sentence is not in itself a finding about the gene and the disease.
cancer (50 papers, 2010 to 2025). A tumor composed of atypical neoplastic, often pleomorphic cells that invade other tissues. "JUN, CXCR4, and WNT5A were the top three interaction DEGs in pathways in cancer; H6PD, FH, and ACO2, which associate with glucose metabolism, were the top three interaction DEGS in metabolic processes." (PMID 37601754, 2023). "Furthermore, we found that silencing of H6PD causes a dramatic decrease in cancer cell migration." (PMID 29295867, 2018). "Follow-on experiments are warranted to uncover the exact mechanism how AGR2 stimulates H6PD activity, thereby contributing to a more aggressive cancer cell phenotype." (PMID 40281598, 2025). "We observed that overall, higher H6PD expression is associated with longer survival, while higher G6PD expression is linked to shorter survival across different types of cancer." (PMID 37867937, 2023). "Although CECS, PCPG, and UCEC are different cancer types and come from different tissues, they share the same result from H6PD downregulation." (PMID 36009075, 2022). "Recent evidence showed that both the glucose-6-phosphate dehydrogenase (G6PD) pathway and a less characterized hexose-6-phosphate dehydrogenase (H6PD) pathway contribute to accelerated cancer cell growth." (PMID 35163973, 2022). "H6PD was found to promote cancer cell proliferation and the modulation of its expression affected GRP78, ATF6 and CHOP, emphasizing its role in ERS regulation." (PMID 35030165, 2022). "The H6PD gene is upregulated in multiple malignancies, and early studies reported that H6PD led to cancer cell growth." (PMID 36009075, 2022). "Many studies have reported that the aberrant activation of G6PD or H6PD is related to tumorigenesis and malignancy in rapidly growing cancer cells." (PMID 33723244, 2021). "Subsequently, we attempted to elucidate the mechanism through which H6PD influences cancer cell growth." (PMID 29295867, 2018). "The H6PD gene is amplified in several types of malignancies, and earlier work pointed toward a potential involvement of the enzyme in cancer cell growth." (PMID 29295867, 2018). "To characterize the role of H6PD in cancer cell proliferation and migration, we analyzed the cellular changes after H6PD silencing." (PMID 29295867, 2018). "The results presented highlight the importance of NADPH production in the ER through H6PD for cancer cells." (PMID 29295867, 2018). "Recently, down-regulation of H6PD with short interfering (si)RNAs in the murine cancer cell lines CT26 (colon) and 4T1 (breast) correlated with a reduction in the overall glucose uptake, as well as a decreased cell proliferation." (PMID 29295867, 2018). "Our study opens new avenues into understanding how compromised ER homeostasis influences cancer cell physiology and proposes H6PD as a potential novel therapeutic target against cancer." (PMID 29295867, 2018). "The fundamental role of H6PD-triggered glucose catabolism in cancer cell survival and growth was confirmed by the effect of enzyme interference on cell viability and proliferation rate." (PMID 27121192, 2016). "Whether higher H6PD activity due to increased AGR2 expression promotes a more aggressive cancer cell phenotype, for example by altering energy metabolism, Ca2+-related processes or UPR and chaperone activation pathways, warrants further investigations." (PMID 40281598, 2025). "H6PD was upregulated in GBM and downregulated in CESC, PCPG, and UCEC, suggesting that H6PD may play an oncogenic role in these four cancers." (PMID 36009075, 2022). "Differential H6PD expression was detected in four cancers: CESC, GBM, PCPG, and UCEC." (PMID 36009075, 2022). "Briefly, H6PD was upregulated in GBM and downregulated in CESC, PCPG, and UCEC, suggesting that H6PD may play an oncogenic role in these four cancers." (PMID 36009075, 2022).
cancer (continued). "This concept agrees with previous evidence in the brain, myocardium, and cancer in which FDG uptake was found to be largely independent of glycolytic flux and strictly linked to the activity of hexose-6-phosphate dehydrogenase (H6PD)." (PMID 31918925, 2020). "In agreement with this hypothesis, G6PD- or H6PD-siRNA simultaneously decreased both d-ribose concentration and culture growth in all studied cancer cell lines." (PMID 33335166, 2020). "The H6PD gene is amplified in 3–4% of pancreatic, sarcomatous, and ovarian tumors and in 1–2% of breast, lung adenocarcinoma, and melanoma tumors, supporting a role of the enzyme in cancer cell growth." (PMID 29295867, 2018). "To evaluate whether H6PD is involved in cancer cell migration, we performed a cell migration assay (Transwell) with a serum gradient as a chemoattractant." (PMID 29295867, 2018). "In this line, FDG uptake might be an index of H6PD activity and its link with cell proliferation more than a surrogate index of glycolysis rate in growing cancer." (PMID 27121192, 2016). "Therefore, we investigated whether H6PD could affect cancer cell proliferation through changes in the UPR." (PMID 29295867, 2018). "Gene set enrichment analysis highlighted enhanced H6PD and AGR2 expression in pathways such as fatty acid metabolism and glycolysis that have key roles in cancer progression and deserve special attention in further research." (PMID 40281598, 2025). "This suggests that H6PD activity and thus luminal PPP promotes an aggressive cancer cell phenotype in different subtypes." (PMID 40281598, 2025). "Differently from MTF, both pharmacologic H6PD impairment by CBX and selective silencing of its expression decreased overall glucose consumption of studied cancer cells suggesting an energetic role for ER metabolism independent from OXPHOS." (PMID 27121192, 2016). "Higher H6PD mRNA levels indicated higher survival in triple-negative cases, whereas higher AGR2 levels correlated with worse outcomes in both triple-negative and HER2-enriched cancers." (PMID 40281598, 2025). "Previous work showed that H6PD down-regulation in 2 murine cancer cell lines decreased overall ATP levels, without affecting mitochondrial oxygen consumption." (PMID 29295867, 2018).
tumor (28 papers, 2007 to 2025). "Collectively, our study suggests that elevated H6PD regulated by OSMR-AS1/hsa-miR-516b-5p correlates with tumor immune infiltration and poor prognosis in GBM patients." (PMID 36009075, 2022). "Tumor tissues with high c-Met expression level in TCGA have increased expression of H6PD, PDK2, PDK4, PDPR, PKLR, SLC2A2 genes whereas decreased expression of GYS1, HK1, HK2, SLC2A1, significantly." (PMID 34059694, 2021). "Moreover, the potential function of H6PD in regulating tumor immune cell infiltration in GBM is incompletely understood." (PMID 36009075, 2022). "Hexose-6-phosphate dehydrogenase (H6PD) has been detected in multiple tumors and is involved in tumor initiation and progression." (PMID 36009075, 2022). "An elevated H6PD-dependent NADPH generation in the endoplasmic reticulum lumen may enhance 17β-HSD7 activity, which has its catalytic site facing this compartment, to promote cholesterol synthesis and tumor growth." (PMID 40281598, 2025).
myopathy (3 papers, 2017 to 2023). A disease of the muscle in which the muscle fibers do not function properly. "In muscle SR, hexose-6-phosphate dehydrogenase (H6PD) reduces NADP+ to produce the NADPH needed for steroidogenesis, and H6PD-deficient skeletal muscle exhibits a myopathy characterized by abnormal SR structure, activation of stress-induced UPR, and dysregulation of Ca2+ metabolism." (PMID 36968274, 2023). "Here we further assess muscle responses to H6PD deficiency to delineate pathways that may underpin myopathy and link SR redox status to muscle wide metabolic adaptation." (PMID 32075690, 2020). "Global and skeletal-muscle specific knockout of H6PD provokes a myopathy characterised by metabolic stress, abnormal SR structure, SR stress and activation of the unfolded protein response." (PMID 32075690, 2020).
H6PD also shares sentences with these, for which no sentence is quoted: infection (9 papers); malaria (5); anemia (3); colorectal cancer (3); leukemia (3); Type 2 diabetes (3); dyslipidemia (2); fungal infection (2); heart failure (2); hyperandrogenism (2); metabolic disease (2); prostate carcinoma (2); renal cell carcinoma (2); Sepsis (2); acute myeloid leukemia (1); age-related hearing loss (1); amyotrophic lateral sclerosis (1); bladder disorders (1); cardiovascular disease (1); cervical cancer (1); childhood asthma (1); chronic heart failure (1); co-infection (1); COVID-19 (1); dengue (1); diabetic retinopathy (1); endometrioid carcinoma (1); escherichia coli infection (1); Glucose intolerance (1); glucose-6-phosphate dehydrogenase deficiency (1).
A further 20 diseases each share a sentence with H6PD in 1 paper.